PKM (pyruvate kinase M1/2)
Diseases named in the same sentence as PKM in open-access papers (continued):
Sharing a sentence is not in itself a finding about the gene and the disease.
cancer (continued). "Interestingly, we found that 25μM curcumin-PECs treatment leads to a significant switch in the PKM splicing from cancer-specific PKM2 to normal PKM1-isoform both at the mRNA level and protein level." (PMID 31675998, 2019). "This study identifies the epigenetic mechanism of PKM-splicing switch in HNC and reports the role of dietary-phytochemical in reverting the splicing switch from cancer-specific PKM2 to normal PKM1-isoform and hence the reduced Warburg effect and growth inhibition of HNC." (PMID 31675998, 2019). "Moreover, this study provides the mechanism to switch the PKM splicing from cancer-specific PKM2-isoform to normal PKM1-isoform, leading to reduced Warburg effect and reduced growth of HNC cells by use of curcumin, a nutraceutical." (PMID 31675998, 2019). "Moreover, in CRC patients, the expression of Lgr5, the cancer stem cell marker, was positively correlated with PKM expression." (PMID 30996297, 2019). "In addition, the relative ratio of PDHB/PKM decreases in cancer tissues across different stages in comparison to the controls." (PMID 31071451, 2019). "Thus, the epigenetic mechanism regulating the PKM splicing can be targeted to revert the cancer-specific isoform to normal splice isoform." (PMID 31675998, 2019). "Notably, the reversal of Warburg effect was achieved by employing a dietary-phytochemical, which inhibits the DNMT3B, resulting in the reduced DNA-methylation at exon-10 and hence, PKM-splicing switch from cancer-specific PKM2 to normal PKM1." (PMID 31675998, 2019). "Our results strongly suggest that PTBP1, hnRNPA1, and SRSF3 controlled cancer-specific energy metabolism at least in part through affecting the PKM gene expression profile via AS, which was clarified by RIP and IP assays, and that these proteins coding RNA would be targets for RNA medicine." (PMID 30279379, 2018). "Our results suggest that the organ-specific distribution of miRNAs is one of the principal means by which miRNA establishes characteristics of a tissue and that dysregulation of these miRNAs results in cancer development through a change in the ratio of PKM isoform expression." (PMID 29695138, 2018). "We therefore hypothesized that the functions of PKM might rely on the metabolic status of cancer cells." (PMID 30257458, 2018). "Also, we examined the regulatory mechanisms of PKM isoform expression by testing each of these miRNAs in human cancer cell lines." (PMID 29695138, 2018). "Western blot analysis at 72 h indicated that treatment with either agent alone reduced the expression level of PTBP1 and modulated the cancer specific energy metabolism through switching of PKM isoform expression from PKM2 to PKM1, thus resulting in a reduction in the PKM2/PKM1 ratio." (PMID 28106737, 2017). "We next examined the intracellular levels of lactic acid and ATP to investigate metabolic changes as a consequence of suppression of the c-Myc/PTBP1/PKMs axis operating in the cancer specific energy metabolism and of switching PKM isoforms from PKM2 to PKM1 by each treatment." (PMID 28106737, 2017). "Recent reports point out decreased activity of pyruvate kinases (PKM) in cancer cells due to preferential expression of PKM2 isoform driven by C-MYC oncoprotein and inhibition of pyruvate dehydrogenase (PDH) activity, as a result of inhibitory phosphorylation catalyzed by PDH kinase (PDK)." (PMID 29262552, 2017). "We found that PTBP1 is the splicer responsible for determining the expression profiles of PKM isoforms; and its action leads to PKM2 expression predominantly in cancer cells, which enables the establishment and maintenance of the cancer-specific energy metabolism." (PMID 28106737, 2017). "It is known that pyruvate kinase in muscle (PKM), which is a rate-limiting glycolytic enzyme, has essential roles in the Warburg effect and that expression of cancer-dominant PKM2 is increased by polypyrimidine tract-binding protein 1 (PTBP1), which is a splicer of the PKM gene." (PMID 26980745, 2016).
cancer (continued). "Based on these findings, we hypothesized that both miRs induced switching of the PKM isoform expression from the cancer-dominant PKM2 to PKM1." (PMID 26980745, 2016). "Although it has already been proved that PKM switching during cancer development occurs in only special cases, the mechanism regulating PKM expression remained largely unknown." (PMID 25721733, 2015). "mTOR signaling has been demonstrated to participate in the switch of PKM isoforms in cancer cells." (PMID 24626155, 2014). "We further demonstrated that elevated PKM2 expression correlated well with the hypomethylation status of intron 1 of the PKM gene in multiple cancer types, suggesting epigenetic regulation by DNA methylation as a major mechanism in controlling PKM transcription in tumors." (PMID 24077665, 2014). "PKM is one of three PKs (PKM, PKL, which is expressed only in the liver, and PKR which is expressed only in erythrocytes) but the only form associated with cancer." (PMID 23451252, 2013). "Cancers maintained the PKM isoform expression according to their tissue of origin." (PMID 21789790, 2011). "This modification inhibited the formation of the active PKM tetramer in cancer cells." (PMID 21907146, 2011). "However, the results agree that total PKM is up-regulated in cancer, which matches the observation of a high glycolytic activity of cancer cells." (PMID 21789790, 2011). "In general, total PKM was expressed at a higher level in the cancer as in the control tissue." (PMID 21789790, 2011). "Furthermore, differences were observed in the expression of several non-canonical and/or embryonic isoforms (HK3, HKDC1, ALDA, GADPH-S, PGK2, and PKM) between patients and controls, as well as in the expression of isoforms considered hallmarks of cancer, such as HK2." (PMID 41009047, 2025). "Consequently, we aimed to ascertain whether ZMYND11 influences the alternative splicing of PKM pre-mRNA and affects the function of cancer cells." (PMID 39341825, 2024). "In addition to these existing inhibitors, exploration of medicine targeting the SFs of PKM to decrease PKM2 production may have great prospects to impair the glycolysis in cancer cells." (PMID 38785973, 2024). "As in other cancers, hnRNPA1-mediated variable splicing of PKM was essential for accelerating cellular glycolysis, and upstream promoters such as lncRNA SNHG6 and ESCO2, and repressors such as RBMX and miR-206 may affect the smooth advancement of this process by interacting with hnRNPA1." (PMID 35879279, 2022). "To systematically identify the functions of the four prognostic PKM transcripts, we identified the differentially expressed genes (DEGs) between patients with the top 25% high expression and bottom 25% low expression of each transcript in all cancers (FDR < 1.0 × 10−5)." (PMID 33478099, 2021). "Moreover, the high expression of different PKM transcripts may induce opposite prognoses in patients with the same cancer." (PMID 33478099, 2021). "Thus, we hypothesized that SRSF10 regulates the PKM splicing favoring the PKM2 isoform, leading to the cancer progression via the Warburg effect." (PMID 34616729, 2021). "Hence, studying alternative splicing processes of PKM in different cancers might provide further understanding about the potential role of PKM in cancer progression." (PMID 33478099, 2021). "Warburg effect is a hallmark of cancer which is characterized by increased glucose uptake and lactate production where the PKM gene regulates the key step of glycolysis, and thus the splicing switch from PKM1 to cancer-specific PKM2 isoforms plays a key role in the Warburg effect." (PMID 34616729, 2021). "Our analysis demonstrated that alternatively spliced transcripts of not only PKM but also other genes should be considered in cancer studies, since it may enable the discovery and targeting of the right protein product for development of the efficient treatment strategies." (PMID 33478099, 2021).
cancer (continued). "Considering that hnRNPA1 can perform the variable splicing of PKM mRNA in order to increase the ratio of PKM2/PKM1 to promote cancer, the interaction with hnRNPA1 to splice the mRNA of PKM may be an important mechanism of SNHG6 that is involved in the metabolic process of CRC." (PMID 32296635, 2020). "The level of mRNAs encoding the M1 and M2 isoforms of pyruvate kinase M (PKM), that catalyzes the transfer of a phosphoryl group from phosphoenolpyruvate (PEP) to ADP generating ATP, are instead similar in both cell lines (isoform M2, associated with cancer) or higher in 5637 (isoform M1)." (PMID 33322565, 2020). "This article proposes the utilization of proteoformics to investigate the role and regulatory mechanisms of PKM proteoforms in OC, facilitate PPPM, and provide insights into the search for biomarkers of this global cancer." (PMID 40137167, 2025). "Epigenetic changes dysregulate HIF-1α and metabolic enzymes like fructose-bisphosphatase FBP1, PKM, and Lactate dehydrogenase A (LDHA) in CAFs, fueling cancer growth." (PMID 40230452, 2025). "In the context of cancer metabolism, one of the most consequential splicing decisions is the production of PKM2 versus PKM1 isoforms from the PKM gene." (PMID 41275207, 2025). "Experiments are in progress to clarify the polyamine-stimulatory mechanisms of eIF5A1, PKM, RPL36A, and RPL22L1 synthesis and functions of RPL36A and RPL22L1 during translation elongation in cancer cells." (PMID 40617352, 2025). "Key enzymes such as hexokinase 2 (HK2), pyruvate kinase M1/2 (PKM), and acetyl-CoA carboxylase alpha (ACACA) were highlighted, reflecting the metabolic reprogramming often observed in cancer cells, known as the Warburg effect." (PMID 40678800, 2025). "Several studies have also identified PKM (pyruvate kinase M, especially the PKM2 isoform) as a crucial oncogene that is upregulated in most types of cancer, including HCC, to promote cancer progression." (PMID 40696822, 2025). "Converting PKM expression from the PKM2 isoform to the PKM1 isoform inhibits the Warburg effect and cancer cell growth." (PMID 39062595, 2024). "The PKM gene produces two protein isoforms through alternative splicing, the M2 isoform (PKM2) is expressed at higher levels than the M1 isoform (PKM1), and PKM2 is the predominant isoform in all human cancer cell lines." (PMID 39070142, 2024). "Mechanistically, SNHG6 induces hnRNPA1 to bind and splice PKM transcript in CRC cells, hence, sensitizing cancer cells for aerobic glycolysis sensitizing cancer cells for aerobic glycolysis." (PMID 37735423, 2023). "HnRNA1 and hnRNPA2 alter the activity of the metabolic enzyme Pyruvate Kinase (PKM) through exon 10 inclusion to increase the PKM2 isoform, thereby increasing the ratio of PKM2/PKM1 isoforms in cancer cells." (PMID 36982162, 2023). "In general, AuNPsp-PEG and AuNPr-PEG tend to increase the expression of enzymes involved in glycolysis, such as HK2 and PKM in PC3 and LNCaP cells, suggesting they play a role in supporting cancer cell survival." (PMID 36899923, 2023). "In cancer cells, PKM2 expression is upregulated, whereas the expression of tissue-specific PKM1 derived from a single PKM gene by alternative splicing of a primary mRNA transcript declines." (PMID 36588153, 2023). "cMyc oncogenic factor regulates the expression of certain hnRNPs (hnRNPA1, hnRNPA2, and PTB), leading to induction of PKM pre-mRNA alternative splicing and concomitant expression of the PKM2 isoform that supports cancer metabolism." (PMID 36909167, 2023). "Cancer cells achieve the metabolic advantage over normal cells by modulating PKM alternative splicing and facilitating the PKM2 expression." (PMID 36810109, 2023). "For example, several proteins were pan-cancer markers present in EVs from nearly all PDX models, including ALB, C1QBP, CDH1, and PKM." (PMID 36470535, 2023). "Cancer cells adjust their metabolism by modulating the PKM alternative splicing and facilitating PKM2 isoform expression." (PMID 36810109, 2023).
cancer (continued). "In cancer carbon metabolism pathways, the Warburg effect obviously appeared in HSCC; glycolysis-related gene HK, PKM, and LDHA were upregulated; and transporter genes GLS, SLC1A5, MCT4 and GLUT1 were upregulated." (PMID 36090994, 2022). "High expression of PKM2, PKM-609, PKM-093, and PKM-883 indicated opposite clinical survival outcome in different cancer types." (PMID 33478099, 2021). "Our results suggest that memantine activates AMPK1/2 significantly (p=0.039 and p=0.0105) that led cells through apoptosis and autophagy by decreasing cancer cell metabolism regulators like HIF1A, B-catenin and PKM as the consequence of this energetic shift." (PMID 34121969, 2021). "We discovered the potential functional and prognostic roles of the three alternatively spliced PKM transcripts in KIRC and different cancers based on systems biology analysis, and partly validated them with in vitro experiments." (PMID 33478099, 2021). "The PKM gene can be alternatively spliced to either the PKM1 or PKM2 transcript, while the PKM2 isoform is almost invariably expressed in cancer cells." (PMID 34290225, 2021). "It is important to note that HIF1A and c-Myc are both known to regulate the expression of tumor-specific isoforms of glycolytic proteins such as GLUT1, HK2, PKM, and LDHA, thereby diminishing the Warburg effect in cancer cells." (PMID 34692483, 2021). "Here, we describe the detailed mechanism of PKM alternative splicing regulation by one of the key tumor suppressor proteins, SMAR1, and its implications in inhibition of cancer cell metabolism and tumorigenesis." (PMID 33863392, 2021). "We identified four different transcripts of PKM including PKM2, PKM-609, PKM-093, and PKM-883 which exhibited opposite prognostic effect in multiple cancer types." (PMID 33478099, 2021). "Both miR-148a and miR-152 were shown to directly target pyruvate kinase M1/2 (PKM2) to counteract glycolytic metabolism of TNBC cells, leading to decreased cancer cell proliferation and angiogenesis." (PMID 33824695, 2021). "We found that seven transcripts had mRNA expression (average TPM) > 5 in at least one cancer type, including PKM1, PKM2, PKM-093, PKM-609, PKM-883, ENST00000562997, and ENST00000568459." (PMID 33478099, 2021). "Cancer cells achieve a metabolic edge over normal cells by regulating PKM alternative splicing and promoting the expression of PKM2." (PMID 33863392, 2021). "It has been previously reported that hnRNPA1 is involved in the variable splicing of PKM mRNA, the upregulation of the ratio of PKM2/PKM1, and the promotion of cancer through aerobic glycolysis, which can be explained through the Warburg effect." (PMID 32296635, 2020). "Intragenic methylation mediated by binding of the protein BORIS leads to an alternative splicing of PKM resulting in the predominant generation of PKM2 and consequent development of cancer-related glycolysis." (PMID 32843908, 2020). "Among all functional groups of proteins associated with SEMGs, we have focused on two key enzymes of cancer-related metabolism—LDHA and PKM." (PMID 33311447, 2020). "PKM2, an embryonic splice isoform resulting from mutually exclusive AS of the PKM pre-mRNA, is re-expressed in many types of tumors and regulates cancer cell metabolism and tumor growth." (PMID 32883335, 2020). "In most of the cancer cells, the PI3K (phosphoinositide 3-kinase)/mTOR (mammalian target of rapamycin) signaling pathway is activated by insulin, thereby up-regulating PKM2 expression through HIF1α-mediated transcription of the PKM gene." (PMID 32195169, 2020). "The study on incidence of tumor and development of carcinoma found that some DEPs indirectly inhibited the occurrence and development of MF, including CLU, GNAS, FZR1, and PKM." (PMID 33299887, 2020). "SRSF3, a splicing factor that is overexpressed in numerous different cancers, also is capable of binding the PKM transcript and promoting the inclusion of exon 10 to promote PKM2 expression." (PMID 30087897, 2018).
cancer (continued). "Our findings indicate that the PKM splicers of PTBP1, hnRNPA1, and SRSF3 were involved in the maintenance of cancer-specific metabolism and also tumorigenesis." (PMID 30279379, 2018). "Through suppression of PTB1, miR-124 induced a switch between PKM isoforms, from isoform PKM2 to PKM1, and increased oxidative phosphorylation and reactive oxygen accumulation in cancer cells." (PMID 28459042, 2017). "Alternate splicing of the PKM gene results in differential expression of PK isoforms, with PKM2 expressed in cells with high rates of nucleic acid synthesis, including most cancer cells." (PMID 29207616, 2017). "Here, we re-analyzed the RNA sequencing data of 25 types of human tumors from The Cancer Genome Atlas Data Portal, and confirmed that PKM2 was the major isoform in the tumors and was highly elevated in addition to the entire PKM gene." (PMID 25738776, 2015). "It is well known that two major transcript isoforms of PKM exist in human: PKM1, expressed in adult tissues;PKM2, expressed in embryonic and adult tissues and also enriched in many cancers." (PMID 26147004, 2015). "We identified a robust upregulation of GLUT1 (SLC2A1), a key rate-limiting factor in the transport of glucose in cancer cells, and genes involved in central glucose metabolism (HK2, ENO1, PKM, and LDHA), PPP (G6PD), and de novo serine biosynthesis pathway (PSAT1, PSPH, and SHMT2)." (PMID 40371988, 2025). "The study also revealed that shikonin (SHK), a natural compound with anti-cancer properties, effectively impedes the molecular interaction between ESM1 and PKM2, thereby inhibiting the formation of PKM dimers and subsequently suppressing glycolysis, fatty acid synthesis, and angiogenesis in OC." (PMID 40137167, 2025). "Notably, PKM1 and PKM2, produced by the PKM gene via alternative splicing, play distinct roles, with PKM2 being highly expressed in most cancer cells and involved in cell proliferation and tumor formation." (PMID 38785569, 2024). "In the present study, we found that PKM and ANXA4 were detected with SNO in human cancer tissue." (PMID 37124724, 2023). "For example, PKM and LDHA are related to central carbon metabolism in cancer." (PMID 37124724, 2023). "We found 16 proteins including HP, PKM, ANXA2, THBS1 that are differentially abundant in GBC tissue (literature search and unpublished data from our lab), in plasma and plasma-derived EVs from GBC or other cancer patients." (PMID 36505879, 2022). "Moreover, inhibition of DNA methylation results in the detachment of BORIS and the shift of PKM2 to PKM1, a result that illustrates the mechanisms that regulate PKM AS in cancer." (PMID 35158828, 2022). "Further, to analyze the role of SRSF10 in PKM and BCLx pre-mRNA splicing, we examined the PKM and BCLx pre-mRNA-splicing pattern in SRSF10 depleted HNC cells and observed the splicing switch of PKM and BCLx gene from cancer-specific (PKM2 and BCLxL) isoform to normal isoform (PKM1 and BCLxs)." (PMID 34616729, 2021). "To further investigate the functional role of these two transcripts, we quantified the mRNA expression of several important marker genes in negative control, PKM-093 and PKM-883 overexpressed PC3 cancer cell lines using qPCR." (PMID 33478099, 2021). "More precisely, cancer cells preferentially splice pre-mRNA of the PKM gene to produce PKM2 rather than PKM1, the former possesses the ability to finely tune its activity in response to nutrient availability and to other different cellular signals." (PMID 33482908, 2021). "However, using RT-qPCR for further validation, we found that only NUP205 and PKM were upregulated in cancer tissues, and the expression of PFKFB1 in cancer tissues was lower than that in adjacent normal tissues." (PMID 32467671, 2020).